TLCD1 (TLC domain containing 1)
Description:
Regulates the composition and fluidity of the plasma membrane. Inhibits the incorporation of membrane-fluidizing phospholipids containing omega-3 long-chain polyunsaturated fatty acids (LCPUFA) and thereby promotes membrane rigidity. Does not appear to have any effect on LCPUFA synthesis.
Tractability: Antibody: UniProt places it where antibodies can reach, with high confidence; its Gene Ontology location is reachable by antibodies, with high confidence; UniProt predicts a signal peptide or a membrane-spanning region.
Gene: Protein-coding gene on chromosome 17 (28,724,348 to 28,727,935, reverse strand). Ensembl gene ENSG00000160606.
Subcellular location: Cell membrane
Gene Ontology:
Molecular function: protein binding
Biological process: membrane assembly; phospholipid homeostasis; plasma membrane organization; regulation of membrane lipid distribution
Cellular component: plasma membrane; membrane
Genetic constraint (gnomAD): Loss-of-function variants: 21 observed, 23.35 expected, observed/expected ratio (o/e) 0.9, 90% interval 0.64 to 1.29. The upper end of that interval is the gene's LOEUF score, 1.29, which puts it in group 5 of 6, group 1 being the genes least tolerant of losing a copy. Missense variants: 344 observed, 338.42 expected, observed/expected ratio (o/e) 1.02, 90% interval 0.93 to 1.11. Synonymous variants: 168 observed, 137.78 expected, observed/expected ratio (o/e) 1.22, 90% interval 1.08 to 1.39.
Homologues: Orthologues: chimpanzee TLCD1 (99% identical), macaque TLCD1 (96% identical), rabbit TLCD1 (91% identical), dog TLCD1 (90% identical), pig TLCD1 (89% identical), rat Tlcd1 (88% identical), mouse Tlcd1 (87% identical), guinea pig TLCD1 (70% identical), zebrafish tlcd1 (37% identical), Caenorhabditis elegans fld-1 (27% identical), Caenorhabditis elegans K12H6.6 (26% identical), Caenorhabditis elegans Y48G8AL.13 (23% identical). Paralogues in human: TLCD2 (29% identical), CLN8 (17% identical), TLCD3A (16% identical), TLCD3B (16% identical), TLCD4 (14% identical).
Diseases named in the same sentence as TLCD1 in open-access papers:
TLCD1 is named in the same sentence as 21 diseases in open-access papers, as found by Europe PMC text mining. Sharing a sentence is not in itself a finding about the gene and the disease. The quoted sentences say what the papers report.
non-alcoholic steatohepatitis (2 papers, 2022 to 2025). "As TLCD1 has been previously implicated in the development of non-alcoholic steatohepatitis and liver cancer, it may be of interest to develop TLCD1 inhibitors based on the structure of thiamine and explore their therapeutic potential." (PMID 39970228, 2025). "Lastly, we demonstrate the biological relevance of our findings in dietary models of metabolic disease, where Tlcd1/2 DKO mice display attenuated development of non-alcoholic steatohepatitis compared to controls." (PMID 36241646, 2022). "Here, the authors show that TLCD1 and TLCD2 proteins mediate the formation of monounsaturated fatty acid-containing PE species and promote the progression of non-alcoholic steatohepatitis." (PMID 36241646, 2022). "Finally, we show that Tlcd1/2 DKO mice fed a high-fat diet (HFD) or a Western diet (WD) have attenuated development of fatty liver disease and nonalcoholic steatohepatitis (NASH), respectively." (PMID 36241646, 2022).
acute myeloid leukemia (1 paper, 2023). Acute myeloid leukemia (AML) is a group of neoplasms arising from precursor cells committed to the myeloid cell-line differentiation. "Notably, TLCD1 expression was found to be reduced in KIRC(Kidney renal clear cell carcinoma) and LAML (Acute Myeloid Leukemia) tumors." (PMID 38559424, 2023).
fatty liver disease (1 paper, 2023). A reversible condition wherein large vacuoles of triglyceride fat accumulate in liver cells via the process of steatosis. "In addition, animal models have provided further validation, demonstrating that TLCD1/2 knockout leads to the development of fatty liver disease and a reduction in the incidence of non-alcoholic steatohepatitis (NASH)." (PMID 38559424, 2023).
hepatocellular carcinoma (1 paper, 2022). A malignant tumor that arises from hepatocytes. "TLCD1 was recently shown to be upregulated in hepatocellular carcinoma, where its expression levels are linked to hepatic inflammation and poor survival outcome." (PMID 36241646, 2022). "We also generated three TLCD1/2 DKO clones in a human hepatocellular carcinoma line to determine whether their function in regulating PE composition is conserved in human cells." (PMID 36241646, 2022).
liver disease (1 paper, 2022). "It will be of interest to investigate TLCD1 and TLCD2 individually in the future to understand the differences in their mechanism of action, and their relative contributions to the liver disease phenotypes observed in the Tlcd1/2 DKO mice in this study." (PMID 36241646, 2022).
non-alcoholic fatty liver disease (1 paper, 2023). "Existing research has revealed the impact of TLCD1 on the development of non-alcoholic fatty liver disease." (PMID 38559424, 2023).
steatosis (1 paper, 2022). Increased lipid within the cytoplasm of cells. "Tlcd1/2 deletion did not affect the levels of hepatic lipids or serum cholesterol in WD-fed mice, but it did reduce the overall incidence of hepatic macrovesicular steatosis." (PMID 36241646, 2022).
cancer (3 papers, 2022 to 2025). A tumor composed of atypical neoplastic, often pleomorphic cells that invade other tissues. "High TLCD1 expression was associated with adverse outcomes in cancers such as ACC, GBM, KIRC, LIHC, THYM and UVM." (PMID 38559424, 2023). "To evaluate the predictive role of TLCD1 in cancer immunotherapy, we examined its association with response to anti-PD1 therapy in GBM and SKCM patients." (PMID 38559424, 2023). "The analysis revealed a significant association between TLCD1 expression and tumor stage in several cancers, including HNSC, KIRC, LUSC, THYM, LIHC, THCA, and TGCT." (PMID 38559424, 2023). "These associations underscore the close relationship of TLCD1 with the tumor microenvironment and its potential as a biomarker for immunotherapy in specific cancer types." (PMID 38559424, 2023). "Our investigation delved into the significance of TLCD1 within the tumor microenvironment (TME) by exploring its association with pan-cancer immune infiltration levels." (PMID 38559424, 2023). "The drugs identified in our screening process require further experimental validation of their associations with various cancers and TLCD1." (PMID 38559424, 2023). "Analysis of the TIMER database revealed that ESCA (2/185), BRCA-Her2 (1/79) and UCEC (11/531) were the top three cancers with the highest rates of TLCD1 gene mutations." (PMID 38559424, 2023). "Analysis of the cBioPortal database analysis showed that missense mutations were the main type of TLCD1 gene mutations in cancer." (PMID 38559424, 2023). "Notably, the association between TLCD1 expression and cancer stage was examined and showed a significant correlation in cancers such as HNSC, KIRC, LUSC, THYM, LIHC, THCA, and TGCT." (PMID 38559424, 2023). "Our investigation aimed to determine whether TLCD1 expression was associated with tumor stage in a pan-cancer context." (PMID 38559424, 2023). "This study aims to provide a comprehensive visualization of the prognostic landscape associated with TLCD1 across a spectrum of cancers, while shedding light on the potential links between TLCD1 expression within the tumor microenvironment and immune infiltration characteristics." (PMID 38559424, 2023). "We further investigated the association between TLCD1 expression and 60 immune checkpoint pathway genes, divided into two classes (inhibitory and stimulatory), using Spearman correlation analysis across the pan-cancer data." (PMID 38559424, 2023). "Thus, TLCD1 may prove valuable as a diagnostic and prognostic biomarker for personalized and precision cancer therapy." (PMID 38559424, 2023). "In this study, we used a variety of bioinformatics techniques to perform a comprehensive pan-cancer analysis of TLCD1." (PMID 38559424, 2023). "Our comprehensive analysis, integrating data from both the TCGA and GTEx databases, revealed distinct and tumor-specific expression patterns of TLCD1 in 33 different cancer tissues." (PMID 38559424, 2023). "This comprehensive study of TLCD1 and RNA modifications contributes to a better understanding of the molecular mechanisms of cancer and provides new insights and avenues for cancer treatment." (PMID 38559424, 2023). "Our analysis revealed significant positive correlations between TLCD1 and drug sensitivity to fulvestrant, econazole nitrate, and amonafide, all of which are clinical drugs used in cancer treatment." (PMID 38559424, 2023). "Our results show a significant correlation between TLCD1 expression and immune responses, suggesting its potential as a valuable prognostic biomarker across multiple cancer types." (PMID 38559424, 2023). "Our analysis of TLCD1 expression levels in relation to overall survival (OS) and disease-free survival (DFS) in cancer patients revealed an association between increased TLCD1 expression in tumor tissues and poor prognosis." (PMID 38559424, 2023). "While our study sheds light on the role of TLCD1 in pan-cancer from a bioinformatics perspective, certain limitations should be acknowledged." (PMID 38559424, 2023).
cancer (continued). "We then evaluated TLCD1 expression levels in different cancer types using multiple databases." (PMID 38559424, 2023). "In addition, we evaluated the relationship between TLCD1 expression and immune infiltration, tumor mutational burden (TMB), microsatellite instability (MSI), and immune-related genes in pan-cancer." (PMID 38559424, 2023). "We used the immune infiltration timer module database of the Sanger tool to demonstrate the association of TLCD1 with various immune cell infiltrations and we examined the correlation between TLCD1 expression and the immune score known as StromalScore in various cancers." (PMID 38559424, 2023). "In addition, we evaluated the prognostic value of TLCD1 expression levels in various cancers by comparing high and low TLCD1 expression cohorts in terms of overall survival (OS) and disease-free survival (DFS)." (PMID 38559424, 2023). "This suggests that TLCD1 expression levels may be a promising indicator to assess the stage of these cancers." (PMID 38559424, 2023). "Therefore, prospective studies of TLCD1 expression and its role in cancer immune infiltration are critical to the development of new drugs." (PMID 38559424, 2023). "Therefore, we initiated an analysis of these diverse TLCD1 gene alterations using the TCGA cancer dataset accessible through cBioPortal." (PMID 38559424, 2023). "However, there remains a gap in comprehensive pan-cancer analyses of TLCD1, and the precise role of TLCD1 in cancer patient prognosis and immunological responses remains elusive." (PMID 38559424, 2023). "We analyzed cancer types where TLCD1 was significantly up or downregulated in tumor tissue." (PMID 38559424, 2023). "Therefore, this article focuses on TLCD1 to explore its relationship with pan-cancer, which has clinical value and significant guiding implications." (PMID 38559424, 2023). "First, although we have established a relationship between TLCD1 aberrant expression and immune cell infiltration and prognosis in human cancers, further investigation is required to elucidate the functional impact of TLCD1 on patient survival through immune responses." (PMID 38559424, 2023). "However, further comprehensive studies are needed to investigate the predictive role of TLCD1 in cancer immunotherapy for individual cancer types in a clinical and mechanistic context." (PMID 38559424, 2023). "In addition, we investigated whether TLCD1 could serve as a critical factor in cancer diagnosis and prognosis." (PMID 38559424, 2023). "Our study revealed correlations between aberrant TLCD1 expression and TMB in 12 cancer types and with MSI in 10 cancer types." (PMID 38559424, 2023). "Second, there is a lack of clinical trials evaluating the use of TLCD1-related therapeutic agents in pan-cancer patients." (PMID 38559424, 2023).
metabolic disease (1 paper, 2022). A congenital disorder (due to inherited enzyme abnormality) or acquired (due to failure of a metabolically important organ) disorder resulting from an abnormal metabolic process. "We observed substantial differences in Tlcd1/2 DKO mouse phenotypes between the two different dietary models of metabolic disease." (PMID 36241646, 2022).
tumor (1 paper, 2023). "Immunohistochemistry showed that TLCD1 expression was higher in most tumor tissues than in normal tissues." (PMID 38559424, 2023). "However, in LAML, immune infiltration levels increased with TLCD1 expression, suggesting that TLCD1 plays an important role in regulating the tumor immune microenvironment (TIME) in these malignancies." (PMID 38559424, 2023). "It is possible that the low expression of TLCD1 in KIRC and LAML is caused by a variety of complex factors, including the biological characteristics of specific tumor types, gene regulatory mechanisms, genomic variations, and the influence of the tumor microenvironment." (PMID 38559424, 2023). "This suggests that TLCD1 may affect tumor development by influencing immune responses and immune infiltration within tumors." (PMID 38559424, 2023). "To assess the potential of TLCD1 in predicting the efficacy of immune checkpoint inhibitor (ICI) therapy, we evaluated its correlation with two well-established predictive biomarkers for immunotherapy, namely, tumor mutational burden (TMB) and microsatellite instability (MSI)." (PMID 38559424, 2023).
TLCD1 also shares sentences with these, for which no sentence is quoted: Barrett esophagus (2 papers); bladder urothelial carcinoma (1); breast carcinoma (1); cutaneous melanoma (1); gastric carcinoma (1); liver cancer (1); lung adenocarcinoma (1); lung squamous cell carcinoma (1); Obesity (1); uterine carcinosarcoma (1); uterine corpus endometrial carcinoma (1).